ZNF746 (zinc finger protein 746)
Description:
Transcription repressor that specifically binds to the 5'-TATTTT[T/G]-3' consensus sequence on promoters and repress transcription of PGC-1-alpha (PPARGC1A), thereby playing a role in regulation of neuron death.
Synonyms: PARIS; FLJ31413
Tractability: PROTAC: UniProt records ubiquitination sites on it; ubiquitination databases record sites on it.
Gene: Protein-coding gene on chromosome 7 (149,472,696 to 149,497,817, reverse strand). Ensembl gene ENSG00000181220.
Subcellular location: Cytoplasm; Nucleus
Subcellular location (Human Protein Atlas): Cytosol; Nucleoplasm
Pathways (Reactome):
Gene expression (Transcription): Generic Transcription Pathway
Gene Ontology:
Molecular function: DNA-binding transcription factor activity; DNA-binding transcription repressor activity, RNA polymerase II-specific; protein binding; RNA polymerase II cis-regulatory region sequence-specific DNA binding; transcription cis-regulatory region binding
Biological process: negative regulation of DNA-templated transcription; negative regulation of transcription by RNA polymerase II; positive regulation of transcription by RNA polymerase II; protein heterooligomerization; protein homooligomerization; regulation of DNA-templated transcription
Cellular component: cytoplasm; cytosol; nucleus
Genetic constraint (gnomAD): Loss-of-function variants: 15 observed, 41.99 expected, observed/expected ratio (o/e) 0.36, 90% interval 0.24 to 0.55. The upper end of that interval is the gene's LOEUF score, 0.55, which puts it in group 2 of 6, group 1 being the genes least tolerant of losing a copy. Missense variants: 810 observed, 903.44 expected, observed/expected ratio (o/e) 0.9, 90% interval 0.85 to 0.95. Synonymous variants: 424 observed, 389.55 expected, observed/expected ratio (o/e) 1.09, 90% interval 1 to 1.18.
Homologues: Orthologues: macaque ZNF746 (98% identical), chimpanzee ZNF746 (97% identical), rabbit ZNF746 (92% identical), mouse Zfp746 (91% identical), guinea pig ZNF746 (91% identical), rat Zfp746 (90% identical), dog ZNF746 (90% identical). Paralogues in human: ZNF777 (38% identical), ZNF398 (34% identical), ZNF407 (14% identical), ZNF416 (13% identical), ZNF408 (13% identical), ZBTB17 (13% identical), ZNF214 (13% identical), ZNF287 (13% identical), ZNF774 (13% identical), WIZ (13% identical), ZNF527 (13% identical), ZNF697 (13% identical), and 38 more.
Diseases named in the same sentence as ZNF746 in open-access papers:
ZNF746 is named in the same sentence as 24 diseases in open-access papers, as found by Europe PMC text mining. Sharing a sentence is not in itself a finding about the gene and the disease. The quoted sentences say what the papers report.
Parkinson disease (9 papers, 2013 to 2025). A progressive degenerative disorder of the central nervous system characterized by loss of dopamine producing neurons in the substantia nigra and the presence of Lewy bodies in the substantia nigra and locus coeruleus. "Sporadic missense variants in RNF133 (MIM# 620556) have been reported in patients with DD and ASD, while missense variants in ZNF746 (MIM# 613914) are reported in patients with Parkinson’s disease, and DD." (PMID 39519104, 2024). "In Parkinson’s disease, parkin loss-of-function mutants lead to ZNF746 overexpression with disturbance of mitochondrial homeostasis and energy metabolism and concomitant loss of dopaminergic neurons." (PMID 31856708, 2019). "For example, ZNF746, a new parkin/interacting substrate also known as PARIS, leads to progressive loss of dopamine and DA neurons in the substantia nigra, a specific hallmark of Parkinson’s disease." (PMID 24294107, 2013). "ZNF746 (PARIS) is originally identified as a substrate of E3 ligase Parkin and its accumulation is associated with Parkinson’s disease." (PMID 32398756, 2020). "It is important to bear this in mind when considering the role of ZNF746 in a certain biological context like in Parkinson’s disease." (PMID 31856708, 2019). "Previous work on members of this subfamily suggested involvement in transcriptional regulation and aberrant ZNF746 overexpression leads to neuronal cell death in Parkinson’s disease." (PMID 31856708, 2019). "ZNF746 attracted our interest because of its involvement in Parkinson’s disease and ZNF777 because of its old evolutionary age." (PMID 31856708, 2019). "ZNF746 (PARIS) has been originally identified as a substrate of E3 ligase Parkin and its accumulation has been observed in brains of Parkinson’s patients." (PMID 32398756, 2020).
bladder cancer (3 papers, 2021 to 2025). "Melatonin inhibits bladder cancer cell migration and invasion by downregulating ZNF746-regulated MMP-9/MMP-2 signaling." (PMID 40756978, 2025). "Another study found that melatonin inhibited the human bladder cancer cell lines HT1376, HT1197, RT4, and T24 by reducing cell proliferation, invasion, and migration through the suppression of the AKT/MMP9 pathway by decreasing ZNF746 protein expression." (PMID 37086261, 2023). "Additionally, ZNF746 is known to promote cancer progression via c-Myc stability in CRC, bladder cancer, and lung cancer." (PMID 34440834, 2021).
colorectal cancer (2 papers, 2021 to 2024). A primary or metastatic malignant neoplasm that affects the colon or rectum. "Hence, in the present study, the underlying apoptotic mechanism of Morusin was explored in association with miR193a-5p mediated ZNF746/c-Myc signaling axis in colorectal cancer cells (CRCs)." (PMID 34440834, 2021).
melanoma (2 papers, 2024 to 2025). A malignant, usually aggressive tumor composed of atypical, neoplastic melanocytes. "Gain- and loss-of-function experiments in NAT10, or in DDX41 and ZNF746, altered the chemosensitivity of melanoma accordingly, and the two target genes also negatively correlated with clinical outcomes." (PMID 39246323, 2024). "The following studies confirmed the correlation between DDX41 and ZNF746 expression and melanoma cell drug resistance as well as disease progression in patients." (PMID 39246323, 2024). "Intriguingly, we found that when DDX41 or ZNF746 expression was forcibly expressed, the anti-melanoma effects of Remodelin were largely diminished in DDX41-OE and ZNF746-OE cells." (PMID 39246323, 2024). "Remarkably, immunohistochemical staining for NAT10, DDX41, and ZNF746 protein on tumor tissues from melanoma patients showed that NAT10 had a positive correlation with these two proteins." (PMID 39246323, 2024). "We further constructed DDX41-overexpressing (DDX41-OE) and ZNF746-overexpressing (ZNF746-OE) melanoma cells to evaluate whether anti-melanoma effects of Remodelin are mediated by DDX41 and ZNF746." (PMID 39246323, 2024). "Intriguingly, ac4C peaks on DDX41 and ZNF746 of melanoma cells were abolished upon NAT10 knockdown." (PMID 39246323, 2024). "Furthermore, we investigated the mechanism of NAT10 promoting the mRNA ac4C modification of C2H2 zinc finger family members DDX41 and ZNF746 in chemoresistance of melanoma and finally evaluated the translational significance of NAT10 inhibitor in overcoming chemoresistance in vitro and in vivo." (PMID 39246323, 2024). "Furthermore, knockdown of DDX41 and ZNF746 sensitized melanoma cells to DTIC treatment." (PMID 39246323, 2024). "In melanogenesis and melanoma (SKCM), suppressing NAT10 inhibits the chemoresistance of melanoma by reducing the expression of the C2H2-ZF family members DDX41 and ZNF746, respectively." (PMID 41316475, 2025). "We measured the protein levels of DDX41 and ZNF746 in our established DR melanoma cells, revealing that increased NAT10 was correlated with elevated DDX41 and ZNF746 proteins." (PMID 39246323, 2024). "Collectively, these data suggest that DDX41 and ZNF746 are correlated with NAT10 expression and play a pivotal role in the treatment response and clinical outcomes of melanoma patients." (PMID 39246323, 2024). "Follow-up analysis also indicated that DDX41 and ZNF746 expressions were negatively correlated with OS and progression-free survival (PFS) of melanoma patients." (PMID 39246323, 2024). "In this study, we disclosed an important role of NAT10 in DTIC resistance of melanoma, mechanistically through promoting NAT10-mediated ac4C modification of DDX41 and ZNF746 mRNAs." (PMID 39246323, 2024). "Meanwhile, the anti-melanoma effects induced by NAT10-knockout were also diminished in overexpressed DDX41 and ZNF746 levels in NAT10-KD cells." (PMID 39246323, 2024). "In summary, our data disclose the role of NAT10 in DTIC resistance of melanoma cells, elucidate the machinery through mediating ac4C modification of DDX41 and ZNF746 mRNAs, and shed light on developing new therapeutic strategies using Remodelin and DTIC for melanoma treatment." (PMID 39246323, 2024).
colon cancer (1 paper, 2025). "Finally, another study showed that morusin inhibits the growth of colon cancer cells by inhibiting the expression of c-Myc and zinc finger protein 746 (ZNF746) in HCT116 cells, interfering with the binding of c-Myc and ZNF746, and upregulating miR-193a-5p." (PMID 40161373, 2025).
neuropathy (1 paper, 2024). A disorder affecting the nervous system that manifests with pain, tingling, numbness, and/or muscle weakness. "Chronic CHIKV patients also show upregulation of genes associated with neuronal death (FOXO3, MCL1, ZNF746, and PICALM) and T-cell differentiation, which may contribute to secondary neuropathy symptoms." (PMID 39596565, 2024).
non-small cell lung carcinoma (1 paper, 2021). A group of at least three distinct histological types of lung cancer, including non-small cell squamous cell carcinoma, adenocarcinoma, and large cell carcinoma. "Kim’s reports showed that inhibition of ZNF746 can inhibit the invasion and metastasis of non-small cell lung cancer cells." (PMID 33929972, 2021).
cancer (3 papers, 2021 to 2024). A tumor composed of atypical neoplastic, often pleomorphic cells that invade other tissues. "Dysregulated expression of ZNF746 can lead to altered transcriptional programs that favor tumorigenesis, making it a potential biomarker and therapeutic target in various cancers." (PMID 39246323, 2024).
tumor (2 papers, 2021 to 2024). "Thus, in the present study, the molecular mechanism of Morusin was explored in CRCs, targeting c-Myc and ZNF746 signaling mediated by miRNA 193a-5p as a tumor suppressor." (PMID 34440834, 2021). "Notably, Morusin upregulated miR193a-5p as a tumor suppressor, while miR193a-5p inhibitor masked the ability of Morusin to reduce the expression of ZNF746, c-Myc, and pro-PARP in HCT116 cells." (PMID 34440834, 2021). "Furthermore, we separated tumor cells from mouse models and found that the DTIC+Rem group had lower protein levels of DDX41 and ZNF746 compared with the DTIC group." (PMID 39246323, 2024).
neurodegenerative disease (1 paper, 2019). A disorder of the central nervous system characterized by gradual and progressive loss of neural tissue and neurologic function. "ZNF746 (synonym PARIS) has been implicated in neurodegenerative disease." (PMID 31856708, 2019).
ZNF746 also shares sentences with these, for which no sentence is quoted: infection (2 papers); Anxiety (1); autism (1); cardiac hypertrophy (1); Insulin resistance (1); lung carcinoma (1); memory impairment (1); neuroblastoma (1); neurological disorders (1); neurotoxicity (1); Obesity (1); Parkinson’s (1); psychiatric disorder (1); sarcopenia (1).